PTPN6 (protein tyrosine phosphatase non-receptor type 6)
Diseases named in the same sentence as PTPN6 in open-access papers (continued):
Sharing a sentence is not in itself a finding about the gene and the disease.
osteoporosis (2 papers, 2021). A condition of reduced bone mass, with decreased cortical thickness and a decrease in the number and size of the trabeculae of cancellous bone (but normal chemical composition), resulting in increased fracture incidence. "It will be worthwhile to further study the roles of PTPN6, CTSD, and FOS in other cells or biological processes except osteoclasts, and explore their significance in the occurrence and development of osteoporosis from the perspective of proteomics and protein modification omics." (PMID 35095774, 2021).
postmenopausal osteoporosis (2 papers, 2021 to 2022). Metabolic disorder associated with fractures of the femoral neck, vertebrae, and distal forearm. "In conclusion, the integrative bioinformatics analysis and real-time PCR analysis were utilized to offer fresh light into the role of monocytes in premenopausal osteoporosis and identified FOS, PTPN6, and CTSD as potential biomarkers for postmenopausal osteoporosis." (PMID 35095774, 2021).
Sepsis (2 papers, 2021 to 2024). Sepsis is defined as life-threatening organ dysfunction caused by a dysregulated host response to infection. "PTPN6 has been shown to inhibit platelet apoptosis and necroptosis during sepsis, and its elevated expression is linked to poor prognosis and increased immune infiltration in cancer." (PMID 39606245, 2024). "AKT1, top up- (FKBP5, SORT1, VNN1, and CST7) and downregulated (PRR5L, SH2B3, SULF2, PLEKHO1, and PTPN6) genes in sepsis were validated using RT-PCR." (PMID 33959663, 2021).
type 2 diabetes (2 papers, 2022 to 2023). "Taken together, our results suggest that methyl syringate, a dual-targeting inhibitor of PTPN2 and PTPN6, is a promising therapeutic candidate for the treatment or prevention of type 2 diabetes." (PMID 37374154, 2023). "In conclusion, our results suggest that methyl syringate, a dual-targeting inhibitor of PTPN2 and PTPN6, exhibits antidiabetic effects and can be used as a functional food ingredient or pharmaceutical supplement to prevent type 2 diabetes." (PMID 37374154, 2023). "As PTPN2 and PTPN6 have been shown to negatively regulate insulin action, the identification of inhibitors of these proteins is considered an effective strategy for the treatment or prevention of type 2 diabetes." (PMID 37374154, 2023). "Therefore, the identification of dual-targeting inhibitors of PTPN2 and PTPN6 could be a potential therapeutic strategy for the treatment or prevention of type 2 diabetes." (PMID 37374154, 2023).
acute myocardial infarction (1 paper, 2025). Necrosis of the myocardium, as a result of interruption of the blood supply to the area. "In acute myocardial infarction mouse models, five genes (Ptpn6, Csf1r, Col6a1, Cyba, and Map3k14) have been implicated in the acute myocardial infarction pathway by regulating DNA methylation, suggesting their potential as early methylated biomarkers for clinical diagnosis." (PMID 40428388, 2025).
Arthritis (1 paper, 2024). Inflammation of a joint. "Tnfaip3, Ptpn6 and Irak3 were differentially expressed in affected paws, spleens, lymph nodes and circulating leucocytes in experimental murine arthritis treated with anti-TNF." (PMID 39116634, 2024).
astrocytoma (1 paper, 2017). "PTPN6 and CUL3 were the key hub genes identified in the astrocytoma relative to the oligodendroglioma." (PMID 28924174, 2017).
bladder tumor (1 paper, 2022). "This research suggests that PTPN6 may play an important role in bladder tumor immunotherapy." (PMID 36211821, 2022).
Castleman disease (1 paper, 2023). Castleman disease (CD) is a benign lymphoproliferative disorder that may present as a localized or multicentric form. "In Castleman disease, improper ETS1, PTPN6, TGFBR2, DNMT3A, and PDGFRB genes cause the appearance of symptoms." (PMID 36766791, 2023).
chronic hepatitis (1 paper, 2018). An active inflammatory process affecting the liver for more than six months. "MAP2K7 and MAPK14 were highly expressed in chronic hepatitis; LAT, SOS2, and BCL‐10 were highly expressed in normal tissues; PTPN6, LCK, and CTLA4 were highly expressed in CS." (PMID 30259695, 2018).
chronic obstructive pulmonary disease (1 paper, 2017). A chronic and progressive lung disorder characterized by the loss of elasticity of the bronchial tree and the air sacs, destruction of the air sacs wall, thickening of the bronchial wall, and mucous accumulation in the bronchial tree. "Rescue of PTPN6 expression or application of a STAT3 inhibitor, effectively protected murine lungs from inflammation and apoptosis, as well as, in part, from the induction of chronic obstructive pulmonary disease (COPD)-like effects." (PMID 29233151, 2017).
colitis (1 paper, 2018). Inflammation of the colon. "Although limited in scope, two published reports suggest a link between PTPN6 in human colitis though." (PMID 30429852, 2018). "For example, a characterization of colitis induction and progression in a PTPN6 T cell conditional knockout mouse has not been published." (PMID 30429852, 2018).
colon adenocarcinoma (1 paper, 2020). "In our study, PTPN5 and PTPN7 were found to be correlated with prognosis of colon adenocarcinoma patients, while PTPN6 and PTPN13 were statistically associated with the prognosis of STAD." (PMID 32536826, 2020).
dementia (1 paper, 2024). Loss of intellectual abilities interfering with an individual's social and occupational functions. "However, CD33 gene expression was found to mediate the association between PTPN6 gene expression and clinical AD dementia." (PMID 39336795, 2024).
esophageal squamous cell carcinoma (1 paper, 2022). Esophageal squamous cell carcinoma (ESCC) is a type of esophageal carcinoma (EC) that can affect any part of the esophagus, but is usually located in the upper or middle third. "Several studies have shown that the DNA methylation-mediated down-regulation of protein tyrosin phosphatase non-receptor type 6 (PTPN6) was linked with the progression of esophageal squamous cell carcinoma and gastric cancer." (PMID 35045088, 2022).
hairy cell leukaemia (1 paper, 2019). "Although not reported in AML, NOX5-derived ROS have been demonstrated to lead to inactivation of Src homology region 2 domain-containing phosphatase 1—SHP1 (PTPN6), another PTP, in a model of hairy cell leukaemia." (PMID 31795243, 2019).
HIV-1 infection (1 paper, 2023). The type species of lentivirus and the etiologic agent of acquired immunodeficiency syndrome (AIDS). "To study the potential role of LysRS in regulating USF2 in HIV-1 infected cells, we examined the mRNA transcript levels of TERT, PTPN6 and TGFb1 when the function of pS207-LysRS was blocked during HIV-1 infection." (PMID 37933844, 2023). "In JurkatS207A cells, the transcription of USF2 target genes PTPN6 and TGFb1 was suppressed during HIV-1 infection compared with JurkatWT cells (top)." (PMID 37933844, 2023).
Hypertension (1 paper, 2022). The presence of chronic increased pressure in the systemic arterial system. "Another interesting gene only present in the patient’s blood data was PTPN6; it was associated with the highest amount of comorbidities, ranging from COPD to hypertension." (PMID 35903362, 2022).
inflammatory skin disease (1 paper, 2025). Inflammatory skin disorders covers a broad category that includes many conditions ranging in severity, from mild itching to grave medical health complications These disorders are common in people of all ages and races. "PTPN6 was found to inhibit the Syk-dependent MyD88 phosphorylation and engagement of RIPK1, TAK1, and apoptosis signal-regulating kinase (ASK) to prevent IL-1α signalling; hence, the absence of Ptpn6 led to inflammatory skin disease development." (PMID 40006996, 2025).
Interstitial pneumonitis (1 paper, 2020). "So-called “motheaten” mice have a recessive Ptpn6 frameshift mutation that leads to an absence of SHP-1 protein, and exhibit severe skin inflammation, as well as interstitial pneumonitis and a range of hematological abnormalities, including hyperproliferative T cells." (PMID 33425916, 2020).
kidney damage (1 paper, 2025). "For example, differential methylation of PQLC2, PTPN6/PHB2, and PRPF8 has been reported to be associated with fibrosis and inflammation leading to kidney damage." (PMID 41357321, 2025).
liver fibrosis (1 paper, 2022). "However, the literature reports that PTPN6 agonist could ameliorate liver fibrosis by upregulating PTPN6." (PMID 35517817, 2022).
non-small cell lung carcinoma (1 paper, 2022). A group of at least three distinct histological types of lung cancer, including non-small cell squamous cell carcinoma, adenocarcinoma, and large cell carcinoma. "Remarkably, phosphatases can influence the response to TKI treatment as reported for PTPN1 (PTP1B), PTPN6 (SHP1) and PTPRC (CD45) for BCR-ABL TKIs treatment in chronic myeloid leukemia or for PTPN11 (SHP2) for acquired resistance to ALK-TKIs in ALK-rearranged non-small cell lung cancer (NSCLC)." (PMID 36698412, 2022).
osteonecrosis (1 paper, 2021). A none disease characterized by death of bone tissue due to a lack of blood supply. "The data of qRT-PCR displayed that PTPN6 mRNA levels in osteonecrosis tissues was decreased compared with control femoral head tissues." (PMID 34910686, 2021).
osteosarcoma (1 paper, 2025). A usually aggressive malignant bone-forming mesenchymal neoplasm, predominantly affecting adolescents and young adults. "Based on the findings, the PTPN family, particularly PTPN6 and PTPN23, appears to play a crucial role in the regulation of osteosarcoma." (PMID 40570022, 2025).
Pan (1 paper, 2023). "We investigated the prognostic significance of PTPN6 in Pan-Cancer by applying the Cox regression model and log-rank test." (PMID 37737713, 2023).
Pancreatic cysts (1 paper, 2018). A cyst of the pancreas that possess a lining of mucous epithelium. "Two DEPs (HOOK1 and PTPN6) were validated by western blot using 19 pancreatic cyst fluid samples (10 LGD, 4 HGD, and 5 invasive IPMN)." (PMID 29713252, 2018).
pancreatitis (1 paper, 2018). Inflammation of the pancreas. "PTPN6 has not been reported in human pancreatic samples but has been observed in PANC-1 cell lines and a rat model of pancreatitis." (PMID 29713252, 2018).
Pneumocystis pneumonia (1 paper, 2024). "characterized B lymphocyte-derived exosomes in fatal Pneumocystis pneumonia (PCP) and found significant alterations in histone H1.3, vimentin, and tyrosine protein phosphatase non-receptor type 6 (PTPN6) levels." (PMID 38994350, 2024).
prion disease (1 paper, 2012). A transmissible disease that is caused by a protein that is able to induce abnormal folding of normal cellular proteins, leading to characteristic spongiform brain changes, which are associated with neuronal loss without an inflammatory response. "The possible mechanistic links of the remaining genes in the SCC (TLR2, NCF1, PTPN6 and B2M) to prion disease are still open." (PMID 23068602, 2012).
psoriasis (1 paper, 2018). An autoimmune condition characterized by red, well-delineated plaques with silvery scales that are usually on the extensor surfaces and scalp. "Several genes reported to be involved in psoriasis pathogenesis including S100A9, S100A8, PTPN22, PTPN6, LAMA4, IL1B and IL12RA were involved in many of these enriched biological processes." (PMID 30092825, 2018).
pulmonary disorders (1 paper, 2017). "We subsequently delineated the function of PTPN6 in Al2O3 NPs-related pulmonary disorders by integrating cellular assays with experimental mouse models." (PMID 29233151, 2017). "The molecular cascades of PTPN6/STAT3/PDCD4 play a vital role in Al2O3 NPs-involved pulmonary disorders." (PMID 29233151, 2017). "Accordingly, we hypothesized that aberrant expression of PTPN6 might be involved in pulmonary disorders induced by Al2O3 NPs in vivo." (PMID 29233151, 2017).
renal carcinoma (1 paper, 2018). A carcinoma arising from the epithelium of the renal parenchyma or the renal pelvis. "Src kinase signaling members were also predominant in the core, including SRC, LCK, LYN, FYN and PTPN6, among which LYN has been causally implicated in renal cancer." (PMID 29861861, 2018).
renal fibrosis (1 paper, 2017). A final common manifestation of a wide variety of chronic kidney diseases characterized by glomerulosclerosis and tubulointerstitial fibrosis. "At PTPN6/PHB2 cg19942083, methylation in kidney cortex associates with lower renal PTPN6 expression, higher eGFR, and less renal fibrosis." (PMID 29097680, 2017).
Sezary syndrome (1 paper, 2008). Sezary syndrome (SS) is an aggressive form of cutaneous T-cell lymphoma characterized by a triad of erythroderma, lymphadenopathy and circulating atypical lymphocytes (Sezary cells). "Of interest, a mutation in the PTPN6 gene coding for SHP-1 in humans has been recently linked to Sezary syndrome, a T-cell cutaneous lymphoma arising from chronic inflammatory state." (PMID 19104650, 2008).
T-cell lymphoma (1 paper, 2024). "Loss of PTPN6 is showed to be linked with higher NF-KB activation in T-cell lymphoma." (PMID 38734673, 2024).
viral pneumonia (1 paper, 2025). Inflammation of the lung parenchyma that is caused by a viral infection. "This analysis identified Sting, Ptpn6, Prkcd, and Cd14 as key genes involved in viral pneumonia." (PMID 40666504, 2025).
tumor (60 papers, 2009 to 2025). "In particular, the recruitment of Ptpn6-deficient OT-I T cells to tumours expressing low-affinity antigen was enhanced compared to control cells." (PMID 38334623, 2024). "Due to its inhibitory activity on STAT3, the gene encoding for PTPN6 can be considered a tumor suppressor gene in AML." (PMID 38534772, 2024). "Knockdown of Ptpn6 expression using short hairpin RNA (shRNA) enhanced OT-I TCR transgenic CD8+ T cell responses to B16 melanomas expressing OVA variant proteins as tumour-associated antigens." (PMID 38334623, 2024). "Shp1 decreased expression and PTPN6 hypermethylation are associated with tumor staging, pathological differentiation and poor survival in patients with esophageal squamous cell carcinoma." (PMID 32596156, 2020). "Before challenging Ptpn6 inducible knockout mice with tumors, we wanted to determine the impact of Shp1 loss in non-tumor-bearing mice." (PMID 33133093, 2020). "Additionally, PTPN6 expression was positively related to the four immunosuppressive cells, including myeloid-derived suppressor cells, tumor-associated macrophage, Tregs, and cancer-associated fibroblasts." (PMID 37737713, 2023). "Conversely, the knockout of PTPN6 significantly enhances the tumor-killing capabilities of these immune cells and boosts antitumor immunity." (PMID 40570022, 2025). "More recently, a similar role for PTPN6 as a tumour-suppressor in solid tumours has also been postulated." (PMID 38334623, 2024). "PTPN6 is a cytoplasmic tyrosine phosphatase that negatively regulate a variety of signaling pathways and is considered a tumor suppressor gene." (PMID 39628694, 2024). "Our functional experiments further confirmed the oncogenic properties of PTPN6 in GBM, as PTPN6 overexpression promoted tumor growth and colony formation in cell lines and nude mice." (PMID 37737713, 2023). "Our findings demonstrated that PTPN6 overexpression played an oncogenic role in GBM and was associated with advanced tumor grades and unfavorable clinical outcomes." (PMID 37737713, 2023). "NGS results from EBV positive DLBCLs revealed the presence of recurrent alterations in B2M (6/9; 66.7%) and PTPN6 (3/9; 33.3%), which were related to the tumor microenvironment and JAK-STAT pathways, respectively." (PMID 36606194, 2022). "Of note, a considerable and durable T cell-mediated suppression of tumor growth was observed when PTPN6 knockdown of OT-I T cells was combined with anti-PD-1 and cytotoxic T-lymphocyte-associated protein 4 (CTLA-4) immunotherapy." (PMID 35957898, 2022). "AP2S1, P3H4 (SC65), SPAG4, PLA2G2F, PTPN6, RAC3, and ETV7 were identified as candidate tumor-associated antigens." (PMID 35814377, 2022). "PIK3R1 and VAV1 are known oncogenes, SYK is a tumor suppressor gene, and PTPN6 has a tumor suppressor role." (PMID 32293263, 2020). "As such, we were unable to assess the effect of Ptpn6 deletion specifically in myeloid cells on tumor growth." (PMID 33133093, 2020). "Lastly, we report that inducible deletion of Ptpn6 drove anti-tumor immunity against several syngeneic tumor cell lines, with corresponding alterations in the frequency and/or activity of both myeloid and T lymphocytes in the tumor immune microenvironment." (PMID 33133093, 2020). "Here we report on the generation of a novel mouse model that facilitated global, inducible deletion of Ptpn6 in adult mice, and we used this model to uncover a role for Shp1 in anti-tumor immunity." (PMID 33133093, 2020). "We also generated a novel mouse model to evaluate the impact of global, inducible Ptpn6 deletion on anti-tumor immunity." (PMID 33133093, 2020). "Overall, this is the first study, which demonstrates that N225K and A550V PTPN6 mutations cause loss-of-function leading to JAK3 mediated deregulation of STAT3 pathway and uncovers a mechanism that tumor cells can use to control PTPN6 substrate specificity." (PMID 26565811, 2015).